EZH2 (enhancer of zeste 2 polycomb repressive complex 2 subunit)
Diseases named in the same sentence as EZH2 in open-access papers (continued):
Sharing a sentence is not in itself a finding about the gene and the disease.
tumor (continued). "MiR-26a acts as a tumor suppressor by inhibiting cell migration and metastasis as well as lowering the expression of the enhancer of zeste homolog 2 (EZH2)." (PMID 33804181, 2021). "In this study, we found that in vivo EZH2i with UNC1999 effectively reduced tumour load in the 5T33MM syngeneic murine model, further emphasising the potential of EZH2 as a target for clinical intervention." (PMID 33579905, 2021). "EZH2 has been found to serve a dual purpose, as either tumour suppressor or oncogene, depending on the type of cancer." (PMID 33712646, 2021). "It is also worth noting that studies suggested the dual role of EZH2 as an oncogene and a tumour suppressor." (PMID 34065087, 2021). "In colorectal cancer mouse models, EZH2 expression was found upregulated in tumour infiltrating Tregs and was shown to be crucial in the Treg-mediated suppression of anti-cancer immunity." (PMID 34439236, 2021). "Since EZH2 upregulation has been earlier correlated with tumor progression, we apprehend that an increase in EZH2 in conjunction with enrichment of open chromatin mark, as observed in Huh-7 cells, is associated with its pro-proliferative effects." (PMID 35127527, 2021). "Regarding the H3K27me3-dependent function, EZH2 catalyzes H3K27me3, which mediates chromatin compaction and results in the transcriptional repression of downstream genes, including tumor suppressor genes." (PMID 35186711, 2021). "EZH2 activity in tumour cells downregulates MHC class I and class II expression on their cell surface, resulting in immune evasion by a reduction in tumour antigen presentation." (PMID 33937922, 2021). "Several studies have shown that inhibition EZH2 expression in tumor cells can suppress the proliferation, migrative and invasive ability, and angiogenesis while increase the apoptotic rate." (PMID 34739394, 2021). "Actually, previous researchers have identified lncRNAs as prognostic markers of PTC, such as TTTY10, LINC00284, RBMS3-AS1, and ZFX-AS1 and five lncRNAs of PPARG, E2F1, CCND1, JUN, and EZH2 for predicting tumor recurrence in PTC." (PMID 34721037, 2021). "As a small molecular inhibitor of EZH2, 3-Deazaneplanocin (DZNep) has been widely studied due to the role of tumor suppression." (PMID 34930462, 2021). "Overexpression of EZH2 leads to increases in H3K27me3, which inhibits the genes related to tumor suppression and cell differentiation (among numerous others)." (PMID 34335707, 2021). "More recent investigation into EZH2 has highlighted its role in the epigenetic repression of tumour-suppressor gene expression." (PMID 33673153, 2021). "CPI-1205, an oral indole EZH2 inhibitor, inhibits tumor growth in B cell lymphoma and several types of solid tumors." (PMID 34001246, 2021). "EPZ-6438 treatment of mice bearing EZH2-mutant non-Hodgkin lymphoma xenografts demonstrated complete and sustained tumor regressions with concurrent diminution of H3K27me3 levels in tumors." (PMID 34617019, 2021). "The U87 MG and PBT24 cell line tumors study shows the effect the U87 and PBT24 tumor differences have on the impact of varying NaDCA concentrations on tumor growth, and on the PCNA and EZH2 expression in the tumor cell." (PMID 33716589, 2021). "In conclusion, we demonstrated that high EZH2 expression in PanNENs correlated with high grade, tumor stage, presence of metastases, and shorter disease-free survival and that EZH2 inhibition impaired cell viability and tumor burden." (PMID 34638497, 2021). "Previous work has shown that extracellular Hsp90 has the epigenetic function of reversing the polycomb function to drive tumor growth and invasion through EZH2, the enzymatic subunit of Polycomb Repressive Complex 2 (PRC2)." (PMID 34946849, 2021).
tumor (continued). "Increased EZH2 expression in tumors is due to the combination of tumor proliferation and H3K27me3, which can ensure H3K27me3 homeostasis." (PMID 34595180, 2021). "The weak but significant (ρ = -0.3028, pFDR = 4.59 × 10–12) association of EZH2 expression with sensitivity to I-BET-762 is surprising, as earlier reports found that EZH2 loss increased tumor sensitivity to bromodomain inhibitors." (PMID 33676569, 2021). "The staining of a BC tumor microarray (TMA) with 119 different samples revealed that the majority of the tumor samples expressed moderate levels of EZH2 and high levels of NFATc1." (PMID 34845197, 2021). "The strong link between high EZH2 expression levels and a high density of CD8+ cells found in our study is consistent with a functionally relevant interaction of EZH2 protein expression and the immune response to tumor cells." (PMID 32303902, 2021). "Recent reports also demonstrated EZH2 as a promising target to suppress tumor immune escape and block viral infection 25, 30-32." (PMID 34512145, 2021). "This was demonstrated in an in vivo tumour model where macrophage anti-tumour function was restored by PD1 checkpoint blockade following EZH2 inhibition." (PMID 33937922, 2021). "Of interest, blocking the PRC2 function through inhibition of EZH2 methyltransferase activity restored antigen presentation at basal level and enhanced antigen presentation after cytokine stimulation in multiple tumor models." (PMID 33859645, 2021). "Treatment of cancer cell lines with a pharmacological EZH2 inhibitor (EZH2i) promoted antigen-specific T cell killing in vitro, and disruption of EZH2 in mouse models leads to re-establishment of a T cell-mediated anti-tumor response." (PMID 34001289, 2021). "Conversely, tumor grade has been shown to be inversely correlated with expression levels of the histone methyltransferase enhancer of zeste homolog 2 (EZH2), being identified in neuroendocrine carcinomas of the lung, but lacking in pulmonary carcinoids." (PMID 33641055, 2021). "EZH2 is supposed to promote tumor progression in both an H3K27me3-dependent and H3K27me3-independent manner in cases of malignant tumor." (PMID 35186711, 2021). "The gene expression of EZH2 were notably corelated with the immune infiltration level of tumor purity, B cell, CD8 + T cell, and neutrophil." (PMID 34077304, 2021). "To further characterize this putative EZH2/TCF3/p21 regulatory axis in vivo, we exploited a subcutaneous xenograft tumor model using KLE cells with EZH2 knockdown or TCF3 knockdown individually or simultaneously." (PMID 34175897, 2021). "In some cancers with EZH2 upregulation, inhibition of the catalytic activity alone is insufficient to stall tumor growth, implicating catalytic-independent roles for EZH2 in cancer progression." (PMID 34617019, 2021). "The result showed that expression of EZH2 in most tumor tissues was expressed highly except for the LAML." (PMID 34381492, 2021). "EZH2 expression is generally found to be increased in metastatic tumors compared to normal tissues or primary tumor specimens." (PMID 34001289, 2021). "In melanoma patients, EZH2 expression was increased in Treg cells infiltrating the tumor compared to Treg cells from the peripheral blood." (PMID 34262562, 2021). "In Bladder carcinoma cells, miR-101 is found in reduced levels correlating with high expression of EZH2 and phenotypically, with tumor growth." (PMID 33602320, 2021). "GSEA demonstrated that EZH2 high expression level group was significantly enriched in “Cell cycle” and “DNA replication”, which are known to be tumor cell proliferation related pathways." (PMID 34341433, 2021). "Both loss and gain-of-function mutations of EZH2 are found in hematological disorders indicating a context-dependent function of EZH2 as an oncogene or tumor suppressor." (PMID 33917538, 2021). "Genetic deletion of Ezh2 in Treg cells from tumor-bearing mice reduced FOXP3 expression and modulated their functionality." (PMID 34262562, 2021).
tumor (continued). "In various cancers, targeting these genes (EZH1 and EZH2) has tumor-suppressive functions affecting tumor cell proliferation, invasion, and metastasis." (PMID 33791221, 2021). "This study showed that miR-126a acts as a tumor inhibitor in UM and suppresses cell viability by targeting the EZH2 gene." (PMID 34381816, 2021). "Western blot analysis confirmed that the expression levels of EZH2 in the tumor tissues were significantly higher than in matched adjacent normal tissues." (PMID 34175897, 2021). "EZH2 inhibition in tumor cells of MCS increases the expression of CSF-1 that, beyond enhancing TAM accumulation, is a crucial TME signal skewing their differentiation toward an M2 phenotype." (PMID 33922336, 2021). "In a recent paper, Xiao and co-workers furthermore identified the histone lysine-N-methyltransferase EZH2 as a possible epigenetic regulator of tumor response to AR-targeting therapy and demonstrated possibilities with its inhibition in the treatment of CRPC." (PMID 34193246, 2021). "It has been reported that EZH2i and BRD4i regimens or triple combinations that include MAPK inhibitors can be used for EZH2-positive tumour patients." (PMID 33986254, 2021). "Mechanistically, we demonstrated that circTP63 competitively bind to miR-217 and promoted EZH2 expression and finally facilitated tumor progression." (PMID 34789260, 2021). "In our HNSCC anti-PD-1 resistant model, systemic administration of Ezh2 inhibitor in combination with anti-PD-1 resulted in suppressed tumor progression." (PMID 33403469, 2021). "Transcriptome analysis revealed that platinum resistant tumors exhibited lower bulk tumor EZH2 expression with low CARM1 (and high MALAT1) co-expression." (PMID 34140011, 2021). "High EZH2 expression and low VASH1 in intrahepatic cholangiocarcinoma were associated with tumor angiogenesis initiation, poor disease-free survival, and poor overall survival." (PMID 34552922, 2021). "PVT1 regulates tumor growth by interacting with the histone methyltransferase enhancer of zeste homolog 2 (EZH2) to function as a repressor of p15 and p16 via trimethylating lysine 27 on histone H3 in gastric cancer." (PMID 34204094, 2021). "Recent research indicates that EZH2 is overexpressed in various tumor tissues and closely related to tumor infiltration, metastasis and prognosis." (PMID 34551671, 2021). "EZH2, a member of the polycomb-group (PcG) family, is reported to be a novel target for tumor control." (PMID 34992654, 2021). "EZH2 expression is also upregulated in tumor-infiltrating Treg cells compared to that in effector T cells or Treg cells in lymph nodes." (PMID 34737746, 2021). "The knockout of EZH2 mimicked the tumor inhibition of miR-26a in UM cells, whereas the reintroduction of EZH2 abolished this effect." (PMID 34381816, 2021). "EZH2 deregulation represents a frequent event in cancer and has been detected in a plethora of tumor entities." (PMID 34943970, 2021). "EZH2 overexpression leads to increases in H3K27me3, with repression of tumor-suppressor genes such as E-cadherin." (PMID 33679454, 2021). "We found that high EZH2 expression correlated with higher tumor grade (p < 0.001), presence of distant metastases (p < 0.001), and shorter disease-free survival (p < 0.001) in PanNEN patients." (PMID 34638497, 2021). "NaDCA impact on U87 MG and PBT24 tumor on proliferating cell nunclear antigen (PCNA) and enhancer of zeste homolog 2 (EZH2) expression in the tumor was different, depending on the NaDCA dose." (PMID 33716589, 2021). "Remarkably, opposite correlations were observed for EZH2, SUZ12, and EED in some cancers, with higher expression being associated with a longer survival, suggesting a tumor suppressor role for PRC2 in those cases." (PMID 34202528, 2021). "We further validated that miR-101-3p attenuated RCC tumor characteristics via targeting EZH2 through rescue experiments." (PMID 34307682, 2021).
tumor (continued). "In Ewing sarcoma, inhibition of EZH2 has demonstrated to promote anti-tumor activity of GD2 specific CAR-T cells and more efficient tumor cell lysis." (PMID 33859645, 2021). "As described in this review, several EZH2 inhibitor molecules have been studied in various tumor cell lines." (PMID 34372908, 2021). "Previous reports showed that EZH2 targets a cascade of tumour suppressors, such as CDX1, FOXC1, LATS2, CDH1 and DAB2IP." (PMID 33336896, 2021). "Enhancer of zesta homologue 2 (EZH2) is an essential component of polycomb repressive complex 2 (PRC2) that contributes to tumor progression and chemo-resistance." (PMID 34140011, 2021). "Two cell-derived xenograft models (U2932: EZH2 WT; SU-DHL-6: EZH2 Y641N) and two patient-derived xenograft models (PDX001: EZH2 WT; PDX002: EZH2 Y641N) were used to assess the anti-tumor activity of drug combination in vivo." (PMID 34503063, 2021). "It is potent against both WT and mutant EZH2 and induces tumor regression in DLBCL mouse xenograft models." (PMID 34617019, 2021). "In tumor-free tissues, both EZH2 and H3K27me3 were only detected in infiltrated lymphocytes and periportal hepatocytes." (PMID 34725436, 2021). "Inhibition of EZH2 blocks proliferation of the drug-resistant stem-cell population, thereby preventing tumor growth." (PMID 34199020, 2021). "Tumor suppressor miRNAs through directly targeting EZH2, inhibit CRC progression include miR-144 and miR-214." (PMID 34288823, 2021). "Taken together, EZH2 inactivation enhanced the recruitment of T cells into the tumor region by upregulating chemokine expression and promoted naïve CD4+ T cells to differentiate into effector Th cells in the short term." (PMID 34737746, 2021). "Together, these data indicated that SNHG22 promotes GC progression through elevating Notch1 and recruiting EZH2 to suppress tumor suppressive genes in vivo." (PMID 34663788, 2021). "Our Gene Ontology enrichment analysis suggests that the tumor-gained H3K4me3 regions exhibiting EZH2 and SUZ12 are enriched with genes related to development processes." (PMID 33916417, 2021). "The potential for developing EZH2 as a drug target to manipulate trained NK cells in tumor immunotherapy applications is an important issue that must be further explored." (PMID 34553850, 2021). "We also evaluated EZH2 transcriptional (RNA sequencing) and protein (mass spectrometry) expression from bulk tumor samples from 336 HGSOC from The Cancer Genome Atlas (TCGA)." (PMID 34140011, 2021). "We further determined the relationship between lnc‐ATB and EZH2 based on 80 pairs of OC and adjacent non‐tumour tissues." (PMID 33336896, 2021). "EZH2 is a key tumor-suppressor gene that induces chromatin densification and epigenetic silence, then leads to tumorigenesis." (PMID 34776951, 2021). "By inhibiting the expression of tumor suppressor genes, EZH2 was shown to govern the acquisition of a prosurvival and pro-proliferative phenotype providing rationale for PRC2 inhibition as a novel antineoplastic strategy." (PMID 33803922, 2021). "The higher EZH2 expression was correlated with tumor size (P = 0.0337) and tumor stage (P = 0.0187)." (PMID 33664859, 2021). "While infigratinib suppressed the growth of the HCC21-0208 tumour overexpressing EZH2, the tumour inhibition was less than that of the control vector tumour, as suggested by the difference in tumour burden over time." (PMID 34156519, 2021). "The results showed that the expression of P16 and P21 was strongly decreased only in tumours of the EZH2-WT group." (PMID 34775498, 2021). "EZH2 is a key regulator of AML65, and the inhibition of EZH2 has been demonstrated to reduce tumor growth and promote apoptosis by regulating T cell polyfunctionality and survival." (PMID 34282207, 2021).
tumor (continued). "Then, given that EZH2 can inhibit the expression of tumor suppressors, we further assess the correlations among these three TFs." (PMID 34966410, 2021). "Our findings demonstrate that EZH2 expression varies based on its interactions with immunologic pathways and tumor microenvironment, impacting the prognostic interpretation." (PMID 34140011, 2021). "The immunomodulatory effects of EZH2 on cells that make up the tumour microenvironment (TME) are also likely to influence response to treatment in both MT and WT disease." (PMID 33937922, 2021). "The H3K27me3-related epigenetic silencing is associated with the levels of the Enhancer of zeste homolog 2 (Ezh2) protein, which induces neoplasia in various tissues." (PMID 33805515, 2021). "Short-term EZH2 depletion or inhibition stalls tumor growth, while prolonged EZH2 depletion drastically alters tumor cell identity and enhances tumor progression." (PMID 34617019, 2021). "In this study, we showed the tumor-suppressive function of EZH2 was mediated by inhibiting the expression of GLS, which played a vital role in cancer metabolic reprogramming." (PMID 34671029, 2021). "We began daily dosing of tumor-bearing mice with the EZH2 inhibitor PF-06821497, starting on day 6 post-implantation." (PMID 34925340, 2021). "Another HMT responsible for H3K27 methylation, EZH2, is bifunctional as either tumor-suppressing or tumor-promoting depending on the cancer type." (PMID 34199020, 2021). "Venn diagrams were used to compare the overlap for gene expression changes between DZNep, that reduced tumor progression and modulated EZH2/H3K27me3 levels, to the other ineffective treatment groups." (PMID 33632299, 2021). "Various studies have revealed oncogenic roles of EZH2 in a wide variety of cancers, and showed that EZH2 overexpression is positively correlated with increased tumor size, invasion, and poor clinical outcomes." (PMID 34815475, 2021). "EZH2 regulates T cell development, differentiation, and function, suggesting that EZH2 also regulates immune homeostasis in addition to tumor suppressor genes." (PMID 34737746, 2021). "Even though EZH2 can act as a tumor suppressor in certain tissues, EZH2 appears to act exclusively as an oncogene in breast cancer." (PMID 33750924, 2021). "The study suggested the cooperation of EZH2 and BRCA1 in regulating ALDH1A1 expression, PCa stem cells, and tumor radioresistance, and the genetic silencing of EZH2 alone or in combination with BRCA1 knockdown decreased the ALDH1A1 level." (PMID 34572930, 2021). "Both EZH2 and BMI1 have also been implicated in pancreatic cancer stem cell maintenance, a functional subset of tumor cells thought to promote PDA chemoresistance and tumor relapse." (PMID 34968245, 2021). "Our findings demonstrated that circTP63 sponged to miR-217 and regulated EZH2 expression and finally facilitated tumor progression in GBC." (PMID 34789260, 2021). "Recent research has reported that FOXD2-As1 performs a tumor inducer by promoting the recruitment of EZH2 to tumor suppressor gene promoters and increasing H3K27me3 modification." (PMID 34739394, 2021). "Based on molecular mechanism related assays, we concluded that FAM83C-AS1 binding to ZRANB1 promoted EZH2 deubiquitination and thereby inhibited EZH2 downregulation, which led to the enhanced protein stability of EZH2 in CRC tumor cells." (PMID 33109776, 2020). "Phosphorylation by AMPK and AKT can both downregulate the enzymatic activity of EZH2, but mediate tumor-suppressive effects and promote tumor progression in different cellular context, respectively." (PMID 32448308, 2020). "One important mechanism by which EZH2 promotes OC cell growth is by regulating p57, a cyclin dependent kinase inhibitor that regulates tumor cell transcription, differentiation, apoptosis, and migration." (PMID 33763107, 2020). "High levels of EZH2 indicate a strong correlation with tumor aggressiveness and poor prognosis in many types of cancers." (PMID 32448308, 2020).